DBX1 (developing brain homeobox 1)
Description:
Could have a role in patterning the central nervous system during embryogenesis. Has a key role in regulating the distinct phenotypic features that distinguish two major classes of ventral interneurons, V0 and V1 neurons. Regulates the transcription factor profile, neurotransmitter phenotype, intraspinal migratory path and axonal trajectory of V0 neurons, features that differentiate them from an adjacent set of V1 neurons (By similarity).
Synonyms: HLX1
Tractability: No criterion of Open Targets' tractability assessment is met for any kind of drug.
Gene: Protein-coding gene on chromosome 11 (20,156,155 to 20,160,475, reverse strand). Ensembl gene ENSG00000109851.
Subcellular location: Nucleus
Gene Ontology:
Molecular function: protein binding; DNA-binding transcription factor activity, RNA polymerase II-specific; DNA binding
Biological process: cell differentiation in spinal cord; regulation of transcription by RNA polymerase II; regulation of DNA-templated transcription
Cellular component: chromatin; nucleus
Genetic constraint (gnomAD): Loss-of-function variants: 12 observed, 19.85 expected, observed/expected ratio (o/e) 0.6, 90% interval 0.39 to 0.98. The upper end of that interval is the gene's LOEUF score, 0.98, which puts it in group 4 of 6, group 1 being the genes least tolerant of losing a copy. Missense variants: 505 observed, 463.76 expected, observed/expected ratio (o/e) 1.09, 90% interval 1.01 to 1.17. Synonymous variants: 241 observed, 207.98 expected, observed/expected ratio (o/e) 1.16, 90% interval 1.04 to 1.29.
Homologues: Orthologues: chimpanzee DBX1 (99% identical), macaque DBX1 (97% identical), pig DBX1 (93% identical), rabbit DBX1 (92% identical), rat Dbx1 (89% identical), dog DBX1 (88% identical), mouse Dbx1 (88% identical), guinea pig DBX1 (86% identical), tropical clawed frog dbx1 (75% identical), zebrafish dbx1b (61% identical), zebrafish dbx1a (56% identical), Drosophila melanogaster Dbx (42% identical). Paralogues in human: DBX2 (33% identical), HLX (31% identical), LEUTX (12% identical).
Diseases named in the same sentence as DBX1 in open-access papers:
DBX1 is named in the same sentence as 15 diseases in open-access papers, as found by Europe PMC text mining. Sharing a sentence is not in itself a finding about the gene and the disease. The quoted sentences say what the papers report.
respiratory failure (3 papers, 2018 to 2023). The significant impairment of gas exchange within the lungs resulting in hypoxia, hypercarbia, or both, to the extent that organ tissue perfusion is severely compromised. "In some cases, loss of a particular factor causes respiratory failure that is traceable to a single respiratory nucleus: for example, neonatal death in Dbx1-null mice is caused by loss of rhythmogenic preBötC neurons." (PMID 29972353, 2018). "Notably, ZFHX, Dbx1, ATP1a2, Tshz, Jmjd3, and Vglut2 have been implicated in causing respiratory failure or death." (PMID 38179140, 2023). "Both MN- and Dbx1-specific cadherin inactivation in mice during a critical developmental window results in perinatal lethality due to respiratory failure and a striking reduction in phrenic MN bursting activity." (PMID 36583530, 2022).
Central apnea (1 paper, 2014). Apnea resulting from depression of the respiratory centers in the medulla oblongata. "Boosting the function of rhythmogenic Dbx1 neurons may mitigate central apneas of prematurity as well as opiate respiratory depression." (PMID 25027440, 2014).
epilepsy (1 paper, 2024). A brain disorder characterized by episodes of abnormally increased neuronal discharge resulting in transient episodes of sensory or motor neurological dysfunction, or psychic dysfunction. "Nav2, Ptpn5, Ldha, and Dbx1 are deemed higher priority as they have a direct biological association with seizures or epilepsy, while Prmt3 and Slc6a5 have an indirect association." (PMID 38862622, 2024).
lung carcinoma (1 paper, 2023). "However, little is known about the biological function of DBX1 in lung cancer." (PMID 37761972, 2023).
obstructive sleep apnea (1 paper, 2014). "Potentially enhancing premotor functionality in Dbx1-derived neurons could ameliorate obstructive sleep apnea." (PMID 25027440, 2014).
respiratory depression (1 paper, 2017). A decrease in ventilation secondary to impaired signals from the central nervous system. "First, Dbx1 preBötC neurons express κ-opioid receptors in addition to μ-opioid receptors that heretofore have been associated with opiate respiratory depression, which may have clinical applications." (PMID 28819234, 2017).
rhabdoid tumor (1 paper, 2021). An aggressive malignant embryonal neoplasm usually occurring during childhood. "Given the lack of knowledge about DBX1’s function in cancer, we first interrogated the Cancer Dependency Map28 and found that DBX1 highly expressed in RMS cell lines with only rhabdoid tumors exhibiting higher expression." (PMID 34535684, 2021).
Sleep apnea (1 paper, 2015). An intermittent cessation of airflow at the mouth and nose during sleep is known as sleep apnea. "We conclude that a subset of Dbx1 IRt neurons is a source of premotor excitatory drive, contributing to the inspiratory behavior of XII motoneurons, as well as a key component of the airway control network whose dysfunction contributes to sleep apnea." (PMID 26687006, 2015).
neurodegenerative disease (3 papers, 2014 to 2025). A disorder of the central nervous system characterized by gradual and progressive loss of neural tissue and neurologic function. "Treatment strategies aimed at rhythmogenic Dbx1 neurons may help overcome the effects of a reduced quantity or efficacy of neurons within the preBötC due to neurodegenerative diseases or aging." (PMID 25027440, 2014).
tumor (2 papers, 2021 to 2023). "Given Dbx1 is the most overexpressed gene in ASPcKO tumors and DBX1 knockdown decreased tumor growth in human FN-RMS cells, we sought to determine how Pten loss regulates Dbx1 expression." (PMID 34535684, 2021). "DBX1 knockdown in both SJRHB015721_X1 and SJRHB012405_X1 PDXs reduced tumor volume and tumor mass." (PMID 34535684, 2021). "We found that both human FN-RMS and FP-RMS had subsets of tumor with high DBX1 expression." (PMID 34535684, 2021).
cancer (1 paper, 2021). A tumor composed of atypical neoplastic, often pleomorphic cells that invade other tissues. "Dbx1 was the most relatively overexpressed gene in ASPcKO tumors and has not been reported to have a role in cancer." (PMID 34535684, 2021).
DBX1 also shares sentences with these, for which no sentence is quoted: Alzheimer disease (1 paper); attention deficit/hyperactive disorder (1); depression (1); Dravet syndrome (1).